CYP2U1 (cytochrome P450 family 2 subfamily U member 1)
Description:
A cytochrome P450 monooxygenase involved in the metabolism of arachidonic acid and its conjugates. Mechanistically, uses molecular oxygen inserting one oxygen atom into a substrate, and reducing the second into a water molecule, with two electrons provided by NADPH via cytochrome P450 reductase (CPR; NADPH-ferrihemoprotein reductase). Acts as an omega and omega-1 hydroxylase for arachidonic acid and possibly for other long chain fatty acids. May modulate the arachidonic acid signaling pathway and play a role in other fatty acid signaling processes. May down-regulate the biological activities of N-arachidonoyl-serotonin, an endocannabinoid that has anti-nociceptive effects through inhibition of fatty acid amide hydrolase FAAH, TRPV1 receptor and T-type calcium channels. Catalyzes C-2 oxidation of the indole ring of N-arachidonoyl-serotonin forming a less active product 2-oxo-N-arachidonoyl-serotonin.
Synonyms: SPG49; P450TEC; SPG56
Tractability: Small molecule: it belongs to a druggable protein family. Antibody: UniProt predicts a signal peptide or a membrane-spanning region. PROTAC: its protein half-life has been measured; a small molecule that binds it is known.
Gene: Protein-coding gene on chromosome 4 (107,931,531 to 107,953,465, forward strand). Ensembl gene ENSG00000155016.
Subcellular location: Endoplasmic reticulum membrane; Microsome membrane; Mitochondrion inner membrane
Subcellular location (Human Protein Atlas): Golgi apparatus; Nucleoplasm; Vesicles
Pathways (Reactome):
Metabolism: Miscellaneous substrates; Synthesis of (16-20)-hydroxyeicosatetraenoic acids (HETE)
Disease: Defective CYP2U1 causes SPG56
Gene Ontology:
Molecular function: arachidonate omega-hydroxylase activity; long-chain fatty acid omega-hydroxylase activity; heme binding; monooxygenase activity; oxidoreductase activity, acting on paired donors, with incorporation or reduction of molecular oxygen, reduced flavin or flavoprotein as one donor, and incorporation of one atom of oxygen; steroid hydroxylase activity; fatty acid omega-1 hydroxylase activity; iron ion binding; oxidoreductase activity, acting on paired donors, with incorporation or reduction of molecular oxygen
Biological process: omega-hydroxylase P450 pathway; cytochrome metabolic process; steroid metabolic process; xenobiotic metabolic process; arachidonate metabolic process
Cellular component: endoplasmic reticulum membrane; mitochondrial inner membrane; cytoplasm
Genetic constraint (gnomAD): Loss-of-function variants: 30 observed, 41.52 expected, observed/expected ratio (o/e) 0.72, 90% interval 0.54 to 0.98. The upper end of that interval is the gene's LOEUF score, 0.98, which puts it in group 4 of 6, group 1 being the genes least tolerant of losing a copy. Missense variants: 642 observed, 651.2 expected, observed/expected ratio (o/e) 0.99, 90% interval 0.92 to 1.05. Synonymous variants: 296 observed, 250.9 expected, observed/expected ratio (o/e) 1.18, 90% interval 1.07 to 1.3.
Gene-disease validity (ClinGen):
ClinGen rates the evidence that CYP2U1 causes each of these diseases.
hereditary spastic paraplegia (autosomal recessive): Definitive. Hereditary spastic paraplegias (HSP) comprise a genetically and clinically heterogeneous group of neurodegenerative disorders characterized by progressive spasticity and hyperreflexia of the lower limbs.
Homologues: Orthologues: chimpanzee CYP2U1 (99% identical), macaque CYP2U1 (98% identical), rabbit CYP2U1 (88% identical), pig CYP2U1 (84% identical), mouse Cyp2u1 (78% identical), rat Cyp2u1 (77% identical), dog CYP2U1 (73% identical), guinea pig CYP2U1 (71% identical), tropical clawed frog cyp2u1 (61% identical), zebrafish cyp2u1 (54% identical). Paralogues in human: CYP2R1 (37% identical), CYP2D6 (37% identical), CYP2J2 (37% identical), CYP2C9 (36% identical), CYP2C19 (35% identical), CYP2A13 (35% identical), CYP2A7 (35% identical), CYP2A6 (35% identical), CYP2C18 (34% identical), CYP2B6 (34% identical), CYP2C8 (34% identical), CYP2S1 (34% identical), and 3 more.
Diseases named in the same sentence as CYP2U1 in open-access papers:
CYP2U1 is named in the same sentence as 38 diseases in open-access papers, as found by Europe PMC text mining. Sharing a sentence is not in itself a finding about the gene and the disease. The quoted sentences say what the papers report.
breast carcinoma (4 papers, 2017 to 2025). "Next, we inspected the potential relevance of CYP2U1 expression with breast carcinoma risk utilizing IHC staining scoring system." (PMID 32850442, 2020). "An immunohistochemical analysis, along with a survival analysis based on clinical–pathological features, showed that CYP2U1 is engaged in the malignant progression of breast carcinoma." (PMID 41020804, 2025). "We also used the same method to evaluate the expression of CYP2U1 in breast cancer tissues with different degrees of differentiation." (PMID 32850442, 2020). "CYP2U1 was first found in a large number of clinical data analysis to be related to the outcome of breast cancer patients." (PMID 32850442, 2020). "After 5 years of follow-up, the prognostic value of CYP2U1 in 219 breast carcinoma patients was determined." (PMID 32850442, 2020). "Hazard ratio (HR) and 95% confidence interval (CI) were applied to estimate the prognostic value of CYP2U1 protein levels in breast cancer patients." (PMID 32850442, 2020). "To expound the connection between CYP2U1 protein levels and the molecular subtypes of breast cancer, we examined the CYP2U1 cytoplasmic staining in 219 primary breast carcinoma." (PMID 32850442, 2020). "Univariate and multivariate Cox regression analysis of CYP2U1 protein expression for 5-year disease-free survival of breast carcinoma patients in tissues microarray." (PMID 32850442, 2020). "Univariate and multivariate Cox regression analysis of CYP2U1 protein expression for 5-year overall survival of breast carcinoma patients in the tissue microarray." (PMID 32850442, 2020). "Our results showed that the protein level of CYP2U1 was distinctly higher in breast carcinoma tissues in comparison with normal tissues (P < 0.0001)." (PMID 32850442, 2020). "The IHC score results showed that the expression level of CYP2U1 in breast carcinoma specimen with pathological grade 3 is higher than that in breast cancer tissues with pathological grade 1–2 (P = 0.0008)." (PMID 32850442, 2020). "Next, we evaluated the correlation of CYP2U1 expression and the prognosis in disparate molecular subtypes of breast carcinoma." (PMID 32850442, 2020). "The fact that CYP2U1 protein was associated with 5-DFS and 5-OS was confirmed via conducting an independent IHC analysis based on 219 breast cancer patients." (PMID 32850442, 2020). "Importantly, survival analysis of breast cancer data manifested that higher CYP2U1 protein expression forecasted poor prognosis among breast carcinoma population." (PMID 32850442, 2020). "However, the biological action of cytochrome P450 2U1 (CYP2U1) in breast carcinoma is little understood so far." (PMID 32850442, 2020). "Firstly, the prognostic value of CYP2U1 in breast cancer was discussed only at histological level." (PMID 32850442, 2020). "In addition, we utilized Kaplan-Meier and COX regression plotter platforms to investigate the effect of CYP2U1 on the clinical outcome of breast carcinoma patients." (PMID 32850442, 2020). "Moreover, Survival analysis of breast cancer patients with lymph node metastasis was implemented employing the KM Plotter platform to measure the clinical value of CYP2U1 in breast carcinoma." (PMID 32850442, 2020). "High expression level of CYP2U1 may be a new prognostic biomarker of breast cancer, and the clinical prognosis was poor." (PMID 32850442, 2020). "Overall, CYP2U1 facilitated malignant biological behavior of breast carcinoma." (PMID 32850442, 2020). "In conclusion, CYP2U1 was dramatically relevant to clinico-pathological characteristic of breast carcinoma, including histologic grade, T stage, the expression of hormone receptors, and HER2, lymph node metastasis and TNM stage, and it was enriched in TNBC tumors." (PMID 32850442, 2020). "This provides more evidence to support that CYP2U1 is closely related to the grade of breast cancer and might have an adverse effect on the differentiation of breast carcinoma cells through some molecular mechanism." (PMID 32850442, 2020).
breast carcinoma (continued). "However, although CYP2U1 mutations have been implicated in certain pathological conditions, for instance, CYP2U1 was highly expressed in colorectal and ovarian cancer, and was closely related to tumor grade, its biological role in breast carcinoma remains to be inquired in depth." (PMID 32850442, 2020). "The others, such as CYP2W1, CYP2S1, CYP2U1, CYP4X1, and CYP4V2, are less specific, but their overexpression in breast cancer has also been found." (PMID 41020804, 2025). "In our research, we demonstrated high cytoplasmic expression of CYP2U1 is an independent prognostic biomarker of 5-DFS and 5-OS of breast cancer patients." (PMID 32850442, 2020). "To assess the protein levels of CYP2U1 in normal and cancerous specimens, we analyzed the TMA of 219 informative breast cancer patients via IHC." (PMID 32850442, 2020). "Importantly, survival analysis showed that higher CYP2U1 protein levels predicted poor 5-year overall survival rate (P < 0.01), 5-year disease-free survival rate (P < 0.05), and 5-year metastatic-free survival rate (P < 0.01) for the entire enrolled breast cancer patients." (PMID 32850442, 2020). "The results demonstrated that CYP2U1 was mainly detected in the cytoplasm of breast cancer tissue, while in non-cancer breast tissue, CYP2U1 was mainly located in the nucleus of cells derived from myoepithelial differentiation." (PMID 32850442, 2020). "Univariate Cox proportional hazard regression analysis confirmed high histological grade, high T stage, low ER and PR, HER2 high-expression, late TNM stage, lymph node metastases and high expression of CYP2U1 were significant relevance in 5-DFS and 5-OS for breast cancer patients." (PMID 32850442, 2020). "Research findings manifested that protein levels of CYP2U1 was dramatically higher in ER- in comparison with ER+ cancer tissues (P = 0.0173), while it was not reach statistical significance in the PR statue (P = 0.1586) and HER2 expression (P = 0.5602) of breast cancer patients." (PMID 32850442, 2020). "Thus, it can be seen that CYP2U1 expression is higher in breast cancer patients with hormone receptor negative." (PMID 32850442, 2020).
Ataxia (3 papers, 2022 to 2025). Ataxia refers to impaired coordination of voluntary muscle movement. "Two siblings were previously reported with an overlap of SPG56- and CLCN2-associated leucoencephalopathy and ataxia, carrying biallelic pathogenic CYP2U1 variants and also biallelic CLCN2 likely pathogenic variants, with azoospermia and MRI compatible with CLCN2, suggesting a true overlap." (PMID 38173802, 2024).
Autosomal recessive spastic paraplegia type 56 (3 papers, 2021 to 2025). "Whole exome sequencing identified a known homozygous pathogenic variant in CYP2U1 gene (c.1168C > T, p.Arg390*), which is a disease-causing mutation in autosomal recessive spastic paraplegia type 56 (SPG56)." (PMID 34828401, 2021). "Hereditary spastic paraplegia 56 (SPG56 MIM 615030, also known as SPG49), is an autosomal recessive form of HSP because of biallelic pathogenic variants in CYP2U1 (MIM # s610670) that may manifest as a pure or a complex form." (PMID 39605873, 2025).
hereditary spastic paraplegia (3 papers, 2022 to 2025). "CYP2U1 mutations are associated with complicated forms of hereditary spastic paraplegia, alterations of mitochondrial architecture and bioenergetics." (PMID 36498943, 2022). "CYP2U1 mutations have been associated with complicated forms of hereditary spastic paraplegia that are characterized by variable conditions of neurologic and extra-neurologic disorders." (PMID 36498943, 2022). "Interestingly, 2 independent families with recessive CYP2U1 mutations leading to hereditary spastic paraplegia (HSP) also present with MacTel." (PMID 37115691, 2023).
breast tumors (2 papers, 2020 to 2025). "More importantly, especially for TNBC patients with high CYP2U1 expression throughout breast tumors, the risk of tumor metastasis was high." (PMID 32850442, 2020). "It was proved that CYP2U1 expression level was negatively connected with the differentiation degree of breast tumors." (PMID 32850442, 2020). "Although less specific, the other orphan CYPs, such as CYP2W1, CYP2S1, CYP2U1, and CYP4X1, exhibit significantly higher expression in breast tumors compared to normal tissues." (PMID 41020804, 2025).
macular dystrophies (2 papers, 2021 to 2025). "CYP2U1 should be included in the panels of genes tested for macular dystrophies, especially in the presence of MacTel and/or neurological manifestations." (PMID 34828401, 2021). "CYP2U1 should be included in panels of genes involved in macular dystrophies." (PMID 39605873, 2025).
calcification (1 paper, 2018). Process by which organic tissue becomes hardened by the physiologic deposit of calcium salts. "Given the complex clinical and radiological picture of this and other reported patients we propose to consider CYP2U1 mutations as the cause of a broader phenotypic spectrum ranging from pure spastic paraparesis (SPG56) to a veritable encephalopathy with cerebral calcification." (PMID 30111349, 2018).
GM1 gangliosidosis (1 paper, 2016). A rare lysosomal storage disorder characterized biochemically by deficient beta-galactosidase activity and clinically by a wide range of variable neurovisceral, ophthalmological and dysmorphic features. "We obtained a genetic diagnosis in 4/9 (44 %) families within known HSP genes (DDHD2 and CYP2U1), as well as perixosomal biogenesis disorders (PEX16) and GM1 gangliosidosis (GLB1)." (PMID 27679996, 2016).
hemorrhagic (1 paper, 2025). "Legrand et al14 observed in 3 patients with homozygote variants in CYP2U1 a maculopathy, reduced central retinal thickness and outer retinal atrophy, retinal pigment epithelium atrophy (1 patient), and a hemorrhagic choroidal neovascular membrane (1 patient)." (PMID 39605873, 2025).
ischemic stroke (1 paper, 2022). A stroke disorder caused by obstruction of blood flow to the brain, due to thrombotic (local blood clot formation) or embolic (due to a blood clot or other material traveling from another site) event. "The involvement of CYP2U1 in the metabolism of LTB4 could have strong physiological consequences in cerebral pathologies including ischemic stroke because CYP2U1 is predominantly expressed in the brain." (PMID 36498943, 2022). "The involvement of CYP2U1 in the metabolism of LTB4 could have strong physiological consequences in cerebral pathological events including ischemic stroke because CYP2U1 is predominantly expressed in the brain whereas CYP4F2/4F3 are mainly expressed in liver and neutrophiles." (PMID 36498943, 2022).
lymph node metastasis (1 paper, 2020). "Similarly, it was further confirmed in multivariate analysis the high histological grade, high HER expression, lymph node metastasis and CYP2U1 high-expression was an important independent predictor of unfavorable 5-DFS and 5-OS." (PMID 32850442, 2020). "Furthermore, high CYP2U1 expression was connected with several clinicopathological parameters consisting of TNM stage, tumor size, histopathologic grading, hormone receptors status, HER2 expression, and lymph node metastasis." (PMID 32850442, 2020).
ovarian carcinoma (1 paper, 2020). A malignant neoplasm originating from the surface ovarian epithelium. "It has been reported that in colorectal and ovarian cancer, CYP2U1 was highly expressed in tumor cells with high pathological grade." (PMID 32850442, 2020). "Recent studies have also found that the expression of CYP2U1 in colorectal and ovarian cancer tissues is higher than that of their adjacent paracancer tissues, and it is related to the malignancy of the tumor." (PMID 32850442, 2020).
retinal diseases (1 paper, 2023). "We compared the significantly dysregulated genes identified in this screen (FDR <0.05) against genes linked to inherited retinal diseases and identified 5 genes: RGR, PRCD, CDH3, GM2A, and CYP2U1." (PMID 37115691, 2023).
Spastic paraplegia (1 paper, 2023). Complete loss of the ability to move the lower limbs accompanied by spasticity of the lower limbs. "Attention to the ocular significance of CYP2U1 was brought about by the ocular phenotype of patients with spastic paraplegia 56, an autosomal recessive neurodegeneration characterized by early-onset progressive lower-limb spasticity and weakness due to mutations in CYP2U1." (PMID 36914277, 2023).
triple-negative breast carcinoma (1 paper, 2020). An invasive breast carcinoma which is negative for expression of estrogen receptor (ER), progesterone receptor (PR), and human epidermal growth factor receptor 2 (HER2). "Additionally, compared with luminal tumors, the CYP2U1 protein content was more abundant in triple negative breast cancer (P < 0.05)." (PMID 32850442, 2020).
tumor (6 papers, 2018 to 2025). "We believe that these findings are important for further analysis of the molecular mechanism underlying the pro-tumor effects of CYP2U1 expression." (PMID 32850442, 2020). "It was proved that CYP2U1 is a hydroxylase which metabolizes arachidonic acid and synthesizes 20-HETE, which is related to the proliferation of tumor cells, and is also upregulated in a variety of cancer." (PMID 32850442, 2020).
cancer (2 papers, 2020 to 2025). A tumor composed of atypical neoplastic, often pleomorphic cells that invade other tissues. "Interestingly, the CYP2U1 protein level was inversely linked with the state of ER, i.e., much higher in ER(-) in comparison with ER(+) cancer tissue." (PMID 41020804, 2025). "Consistent with previous studies, our study also indicated the protein content of CYP2U1 is prominently higher in breast cancerous tissues than in non-cancer tissues, and expression pattern of CYP2U1 had also changed from the original nuclear expression to cytoplasm expression." (PMID 32850442, 2020). "The results of statistical analysis about staining scores exposed that CYP2U1 protein level was obviously elevated in TNBC tissues compared with luminal-type carcinoma specimens(P = 0.0034), while pairwise comparisons of other molecular types were not statistically significant." (PMID 32850442, 2020). "Taken together, these researches suggested that there may be a link between increased CYP expression and cancer-promoting effects, which potentially explained the shorter 5-RFS, 5-OS, and 5-MFS observed in patients with high CYP2U1 expression." (PMID 32850442, 2020). "The involvement of CYP2U1 in the metabolism of LTB4 could have significant physiological consequences, as LTB4 is an important inflammatory mediator involved in the pathogenesis of many diseases, including cancer." (PMID 41020804, 2025). "Using this feature, in pathological diagnosis, the IHC pattern of CYP2U1 expression may to some extent be served to distinguish cancer from non-cancer tissue in the future." (PMID 32850442, 2020).
CYP2U1 also shares sentences with these, for which no sentence is quoted: Dystonia (3 papers); colorectal cancer (2); alcoholic liver diseases (1); Azoospermia (1); bovine tuberculosis (1); cerebellar ataxia (1); chronic progressive external ophthalmoplegia (1); cognitive delay (1); Encephalopathy (1); glioblastoma (1); hereditary spastic paraplegia 56 (1); infection (1); Intellectual disability (1); Leukoencephalopathy (1); lung carcinoma (1); macular telangiectasia type 2 (1); neuropathy (1); Photophobia (1); Spastic paraparesis (1); Telangiectasia (1); Visual impairment (1).